ERBB2 (erb-b2 receptor tyrosine kinase 2)
Diseases named in the same sentence as ERBB2 in open-access papers (continued):
Sharing a sentence is not in itself a finding about the gene and the disease.
leukemia (67 papers, 2011 to 2026). A malignant (clonal) hematologic disorder, involving hematopoietic stem cells and characterized by the presence of primitive or atypical myeloid or lymphoid cells in the bone marrow and the blood. "In aggregate, we report three functional ERBB2 mutants in leukemia that are highly sensitive to irreversible ErbB inhibitors in our cytokine-independent cellular assay." (PMID 32366937, 2020). "Interestingly, we have identified the IL-15 production pathway to be activated in leukemia cells cultured in the 3D BM niche-like AML model, with different associated genes upregulated, including EGFR, IGF1R, MET, RELB, and ERBB2." (PMID 37932837, 2023). "While the functional significance of these mutations is undetermined, MAP3K10 and MAP4K1 lead to activation of the JNK pathway, which could contribute to leukemia cell growth downstream of ERBB2." (PMID 32366937, 2020). "Transcriptome profiling of human leukemia HAP1 cells revealed that TRPM7 plays a regulatory role in the expression of several transcripts, including HER2 (ERBB2)." (PMID 39513908, 2024). "In our 3D BM niche-like AML model, leukemia cells demonstrated an upregulation of FGF2, FOS, and ERBB2, which acts on and activates Twist1 and Snail2." (PMID 37932837, 2023). "Exposure of ErbB2-negative targets such as K562 leukemia cells to UniCAR-NK cells in the presence of multivalent TMs with two or more E5B9 sequences did not result in enhanced basic NK cell activity, making increased tonic signaling by TM-induced higher order UniCAR complexes unlikely." (PMID 36688995, 2023). "Although kinase domain mutations of ErbB receptors are uncommon in acute leukemias, in vitro inhibition of ErbB2 reduces cell proliferation especially when combined with BCR-ABL tyrosine kinase inhibitors in Ph+ ALL, suggesting a role for ErbB signaling pathway activation in leukemia." (PMID 26269779, 2015). "Our preliminary results and other studies have shown that ErbB2 transcripts, but not EGFR transcripts, were detectable in leukemia cell lines other than K562 (data not shown)." (PMID 22216158, 2011).
thyroid cancer (63 papers, 2011 to 2026). "Comprehensive molecular analysis of canine thyroid cancer (TC) uncovers distinct oncogenic pathways: ERBB2/HER2 activation in follicular TC, and RET signaling in medullary TC, mirroring human TC and highlighting species-specific mechanisms." (PMID 41353477, 2025). "For instance, high ERBB2 expression is one characteristic phenotype of thyroid cancer resistance to MEKi selumetinib." (PMID 36437939, 2022). "Thus, a more comprehensive prospective study is of value in the future to detail the role of ERBB2 in thyroid cancer." (PMID 36437939, 2022). "In thyroid cancer, however, the deep-going research on ERBB2 is limited." (PMID 36437939, 2022). "miR-497 and miR-375 were demonstrated to be down-regulated in thyroid cancer and target AKT3 and ErbB2 receptor tyrosine kinase 2 (ERBB2), respectively." (PMID 33158279, 2020). "The HER/ErbB family of receptors including EGFR (HER1/ErbB1), HER2 (ErbB2), HER3 (ErbB3) and HER4 (ErbB4) plays a critical role in tumorigenesis including thyroid cancer." (PMID 27517321, 2016). "Additionally, new targets are now being explored in the field of thyroid cancer, such as MEK, ERBB2/HER2, ALK or SSTR in order to increase the therapeutic possibilities and offer the adequate directed treatment to the patients." (PMID 32668761, 2020). "Interestingly, phosphorylation of other RTKs such as EGFR, ERBB2, and FLT-3 have recently been shown to be promoted when EcSOD is overexpressed in thyroid cancer cells." (PMID 29296173, 2017).
head and neck squamous cell carcinoma (62 papers, 2011 to 2025). A squamous cell carcinoma that arises from any of the following anatomic sites: lip and oral cavity, nasal cavity, paranasal sinuses, pharynx, larynx, and salivary glands. "However, 31% of cancers showed ERBB2 deficiency in tumor samples, including prostate adenocarcinoma, kidney chromophobe, head-neck squamous cell carcinoma, renal clear cell carcinoma, colon adenocarcinoma, kidney renal papillary cell carcinoma, and lung squamous cell carcinoma." (PMID 36172165, 2022). "We previously demonstrated that API was able to selectively inhibit the tyrosine phosphorylation of specific residues of EGFR and ErbB2 in head and neck squamous cell carcinoma." (PMID 28674496, 2017). "A significant tumor specific overexpression of all four ErbB receptors including EGFR, ErbB2, ErbB3, and ErbB4 has been reported in head and neck squamous cell carcinomas (HNSCC)." (PMID 24886178, 2014). "The combination of HER2/neu (also known as ErbB-2) CAR-T cells and oncolytic adenovirus-expressing anti-PD-L1 and IL-2 remarkably improved survival compared with either form of therapy alone in head and neck squamous cell carcinoma xenograft mice." (PMID 33086754, 2020).
chronic myeloid leukemia (60 papers, 2007 to 2025). "Abl in chronic myeloid leukemia (CML), ErbB2 in some breast cancers, and EGFR in some non-small cell lung cancer are a few examples of such mono-driver cancers." (PMID 32069833, 2020).
renal cell carcinoma (58 papers, 2008 to 2025). "This consequence is partially consistent with previous studies, such as those involving ERBB2, which is rarely expressed in renal cell cancer and is involved in RCC oncogenesis." (PMID 36360294, 2022). "Additionally, in renal cell carcinoma, concomitant overexpression of the EGFR and erbB-2 was correlated with dedifferentiation and metastasis." (PMID 33803354, 2021). "Importantly, a high rate of severe toxicities was observed for CAR-T therapies targeting TAAs including carbonic anhydrase IX (CA IX) in renal cell carcinoma (RCC) and ERBB2 in metastatic CRC." (PMID 34572009, 2021).
salivary gland cancer (56 papers, 2008 to 2025). A primary or metastatic malignant neoplasm that affects the major or minor salivary glands. "Patients with SCC were subjected to immunotherapy for high TMB, whereas those with salivary gland cancers were treated with molecularly targeted drugs against ERBB2 mutations." (PMID 35884537, 2022). "Pathogenic ERBB2 mutations were identified in three patients with salivary gland cancer, which provides a match to trial therapies with level 3a/3b evidence." (PMID 35267442, 2022). "In another case, a highly pretreated patient with salivary gland cancer received trastuzumab deruxtecan following molecular assessment ErbB2 amplification, as recommended by the MTB." (PMID 39323465, 2024). "ERBB2/3 has been shown to be overexpressed in breast, ovarian, bladder, stomach, and salivary carcinomas, thereby impairing normal cellular control mechanisms and giving rise to malignant tumor cell transformation." (PMID 24774301, 2014). "In agreement with these evidences it is reasonable to investigate ErbB2 cancer vaccine approaches with the aim to improve the objective tumor inhibitory response in salivary gland carcinomas." (PMID 24886178, 2014). "ErbB1 and ErbB2 are also frequently overexpressed in salivary gland cancers and this has provided the rationale for clinical trials with trastuzumab, cetuximab, gefitinib and lapatinib." (PMID 18542074, 2008). "In agreement with both EGFR and ErbB2 overexpression, cetuximab and trastuzumab, which target EGFR and ErbB2, respectively, represent important tools for treatment of salivary gland carcinomas." (PMID 24886178, 2014). "ErbB2 overexpression was observed in about 20% of patients with salivary duct cancer (SDC), a rare high-grade aggressive tumor subtype of salivary gland carcinoma." (PMID 24886178, 2014).
mucinous carcinoma (54 papers, 2008 to 2025). "While high level amplification of ERBB2 was evident in the IDP and DCIS components, the mucinous carcinoma component showed only a low level gain of ERBB2 (validated by SISH), and an additional 13q loss." (PMID 32195332, 2020). "ERBB2 mutation is commonly present in both infiltrating lobular carcinoma and mucinous carcinoma." (PMID 32226776, 2020). "Instead, activation status of EGF receptors might be more important, while in mucinous adenocarcinomas, the constitutive activation of the ERBB2 pathway, which is caused by persistent up-regulation of ERBB2 and ERBB2 mutations, might contribute to the MUC5AC overexpression." (PMID 22676183, 2012). "All synchronous carcinomas were ER+, and three carried an ERBB2 amplification (one papillary DCIS with mucinous carcinoma and two HG DCIS/IDC)." (PMID 32195332, 2020). "Based on their pathological reports of ERBB2+ GC, all of those are intestinal-type GC in traditional Lauren classification, such as tubular adenocarcinoma, papillary adenocarcinoma, and a few mucinous adenocarcinomas." (PMID 30123134, 2018). "One of the EGF receptor family members, ERBB2, has been shown to be overexpressed in lung mucinous adenocarcinomas." (PMID 22676183, 2012). "ERBB2 amplification was found in 33.3% of mucinous carcinoma cases." (PMID 32813918, 2020). "Despite the moderate frequency of amplification events, activating mutations of ERBB2 have not previously been implicated in mucinous carcinoma pathogenesis." (PMID 25986173, 2015). "Interestingly, overexpression of EGF receptor 2 (ERBB2, HER2) has been demonstrated in primary lung mucinous adenocarcinomas, which were characterized by KRAS activating mutations as well as very high levels of MUC5AC production." (PMID 22676183, 2012). "Mucinous carcinoma (MC) of the ovary is rare, accounting for only 4% of cases, with the majority being diagnosed at stage I. Key genetic features of MC include mutations in KRAS, present in 40–50% of cases, and HER2/ERBB2 amplification, which occurs in 19% of cases." (PMID 39061859, 2024). "Although most of the synchronous carcinomas were ERBB2 non-amplified, one ERBB2 amplified case, S11 (with both IG papillary DCIS and mucinous carcinoma components), was shown by multiple shared CN gains and losses to be clonal with the atypical IDP lesion." (PMID 32195332, 2020).
multiple myeloma (54 papers, 2013 to 2025). "The main goal of the present study was to examine if the RNA-sequencing (RNAseq)-based ERBB2/HER2 expression level in malignant plasma cells from multiple myeloma (MM) patients has clinical significance for treatment outcomes and survival." (PMID 37373090, 2023). "Usually a single test (for example, ERBB2/HER2 amplification testing) or a limited panel of approximately five tests (for example, chronic lymphocytic leukemia panel, myeloma panel)." (PMID 27784327, 2016). "The dual ERBB2/EGFR inhibitor also effected majorly via EGFR pathway in myeloma cells." (PMID 25894462, 2015).
Hypertension (51 papers, 2012 to 2025). The presence of chronic increased pressure in the systemic arterial system. "Ibrutinib-specific off-targets LCK, JAK3, and FLT3 were predicted to trigger inflammation processes related to hypertension; ERBB2, BLK, SRC, and CSK were predicted to trigger oxidative stress and endothelial dysfunction; and CSK were predicted to trigger the RAAS overactivation." (PMID 40744952, 2025). "Similarly, there were 4 consistent circRNAs between ICH and hypertension (HTN) in our previous study; 2 of them were consistently altered in the two comparison groups, including hsa_circ_0027725 and a novel circRNA (host gene ERBB2) we named circERBB2." (PMID 36523430, 2022).
medulloblastoma (50 papers, 2012 to 2025). A malignant, invasive embryonal neoplasm arising from the cerebellum. "In most benign meningiomas, however, ErbB4 is underexpressed and co-expression of ErbB4 with ErbB2 has been associated with poor prognosis in medulloblastoma and with increased proliferation index in ependymomas." (PMID 36119496, 2022). "In the medulloblastoma cell line Daoy cells, Erb-B2 Receptor Tyrosine Kinase 2 (ERBB2) overexpression, an event associated with invasiveness and poor prognosis, increased the migration across basement membranes in vitro and the expression of prometastatic genes, such as S100A4." (PMID 33918416, 2021). "Previously, medulloblastomas were classified into subgroups based on ErbB2 expression levels measured via immunohistochemistry." (PMID 39022728, 2024). "Overexpression of ErbB4 in conjunction with ErbB2 correlates with poor prognosis in medulloblastoma patients." (PMID 36119496, 2022). "S100A4 protein serves as a direct signaling target of receptor tyrosine kinase 2 (ERBB2) in medulloblastoma through a pathway involving phosphatidylinositol 3 kinase AKT (PI3K/AKT), which is ultimately blocked by the ERBB tyrosine kinase inhibitor OSI774." (PMID 34148033, 2021). "Receptor tyrosine-protein kinase ERBB2 (HER2) is a well-known immunotherapy target that is overexpressed in multiple adult and pediatric cancers, including approximately 40% of medulloblastoma." (PMID 29712574, 2018). "ERBB2 has been found to be expressed in a large proportion of medulloblastoma and to be prognostic, however attempts to target it therapeutically have not been successful in the relapsed setting." (PMID 29880060, 2018). "High expression levels of MET and ErbB2 are correlated with poor clinical outcome in medulloblastoma patients." (PMID 26496080, 2015). "Expression of EGFR and ErbB2 is in agreement with previous studies in medulloblastoma cell lines and primary tissue expression, in which expression of EGFR and ErbB2 was detected in varying percentages." (PMID 26496080, 2015). "Previously with kinome profiling, we observed MET and EGFR/ErbB2 peptide activity in primary medulloblastoma samples." (PMID 26496080, 2015). "More interestingly, high expression levels of both MET and ErbB2 in primary medulloblastoma tissue are correlated with poor clinical outcome in patients." (PMID 26496080, 2015). "ErbB2 is expressed in more than 80% of tumors and upregulates prometastatic genes and increases the migration of medulloblastoma cells 2,9,10." (PMID 25052069, 2014). "ErbB2 overexpression has been shown to be one of the mechanisms involved in Akt activation in medulloblastoma cells." (PMID 25052069, 2014). "Furthermore, we show that EGFR and ErbB2 are highly and ErbB3 and ErbB4 are hardly expressed on the cell surface of our medulloblastoma cell lines." (PMID 26496080, 2015). "Flow cytometry analysis revealed that MET (mean±sd: 74.9% ± 13.9%), EGFR (mean±sd: 77.4% ± 10.9%) and ErbB2 (mean±sd: 67.8% ± 10.3%) are highly expressed in all medulloblastoma cell lines, whereas ErbB3 (mean±sd: 4.0% ± 3.6%) and ErbB4 (mean±sd: 1.5% ± 2.1%) are barely expressed at all." (PMID 26496080, 2015). "Thus, aberrant EGFR/ErbB2 signaling has become an attractive therapeutic target for medulloblastoma." (PMID 25052069, 2014). "It was also reported that ERBB-2 and ERBB-4 are highly expressed in aggressive forms of medulloblastoma." (PMID 24986561, 2014). "The levels of ERBB2 and S100A4 tightly correlated also in samples of primary medulloblastoma." (PMID 33918416, 2021). "Various receptor tyrosine kinases (RTK’s) are expressed in medulloblastoma, including vascular endothelial growth factor receptor-2 (VEGFR-2), platelet-derived growth factor receptor α (PDGFRα), hepatocyte growth factor receptor (MET) and epidermal growth factor receptor 2 (ErbB2)." (PMID 26496080, 2015).
medulloblastoma (continued). "ErbB2 has been suggested to be involved in the migration of medulloblastoma cells 2,9,10, and in our studies DAOY cells treated with EGF were highly motile, suggesting that activation of the EGFR signaling cascade may play a role in medulloblastoma cell migration." (PMID 25052069, 2014). "Moreover, medulloblastoma exhibits increased expression of genes such as MYO18B (often absent in other tumors), ERBB2, ERBB4, BMI1, and KLHDC8A (OMIM 607295; OMIM 164831; OMIM 614503; OMIM 155255; OMIM 164870; OMIM 600543)." (PMID 39022728, 2024).
pancreatic adenocarcinoma (46 papers, 2009 to 2025). "The finding indicates that loss of ErbB2 leads to decrement of MAPK activation of the cells of pancreatic adenocarcinoma patients." (PMID 29511477, 2017). "Of 1,791 patients with pancreatic adenocarcinoma, 36 (2.0%) had an ERBB2 amplification, 26 (72.2%) of whom had a KRAS alteration." (PMID 38406801, 2024). "Our case series illustrates that certain patients with ERBB2-amplified pancreatic adenocarcinoma may respond to anti-HER2 therapy and gain several months of prolonged survival." (PMID 38406801, 2024). "A role for MMP10 downstream of ErbB2 has been also demonstrated in pancreatic adenocarcinoma." (PMID 27351228, 2016).
pancreatic ductal adenocarcinoma (46 papers, 2009 to 2026). An infiltrating adenocarcinoma that arises from the epithelial cells of the pancreas. "There are several receptors and pathways associated with the development of pancreatic ductal adenocarcinoma (PDAC), including the EGFR, the receptor protein tyrosine kinase, the NOTCH signaling system, the ERBB2, and the TGF bate pathway." (PMID 38532833, 2023). "A few of these recurrent neoantigens are from known oncogenic drivers, for example, PIK3CA, MAPK1, ERBB2, ERBB3, and also from the KRAS G12D mutation, which we recently identified as a promising recurrent neoantigen-based immunotherapy target in pancreatic ductal adenocarcinoma." (PMID 28670312, 2017). "Therefore, we presume that YY1 suppresses invasion and metastasis of pancreatic ductal adenocarcinoma by downregulating MMP10 in a MUC4/ErbB2/MEF2C-dependent mechanism." (PMID 24884523, 2014). "As far as ME2C is concerned, it demonstrated its activation by the MAPK p38 in inflammation in monocytic cells, whereas downregulation of the MUC4/ErbB2/p38/MEF2C‐dependent pathway was shown to suppress invasion and metastasis of pancreatic ductal adenocarcinoma." (PMID 31930767, 2020).